GLS (glutaminase)
Diseases named in the same sentence as GLS in open-access papers (continued):
Sharing a sentence is not in itself a finding about the gene and the disease.
tumor (continued). "The mitochondrial enzyme glutaminase in particular is under intense investigation in many tumor models, with an immense amount of time invested in the development of selective and non-toxic small-molecule glutaminase inhibitors with superior metabolic stability and pharmacodynamics." (PMID 27462863, 2016). "However, despite mechanistically promising in vitro data, the synergistic effect endowed by the enolase and glutaminase inhibitors could not be entirely recapitulated in vivo in both orthotopic (intracranial) and subcutaneous tumor models." (PMID 34172075, 2021). "The combined treatment with the glutaminase inhibitor CB-839 and the PI3K/aldolase inhibitor BKM120 consistently reduces cell growth of both A549 and HCT116 tumor xenografts, leading to a significant tumor reduction and prolonged survival without associated toxicity." (PMID 33005401, 2020). "Using patient-derived tumor and adjacent non-cancerous tissues, we confirmed that expression of the SLC1A5, SLC7A5, and SLC38A1 is a rescue mechanism induced by GLS inhibition." (PMID 40707944, 2025). "Using patient-derived tumor and adjacent non-cancerous tissues, we found that expression of the SLC1A5, SLC7A5, and SLC38A1, and NUPR1 is a rescue mechanism induced by GLS inhibition." (PMID 40707944, 2025). "Knockdown of AAK1 substantially suppressed tumor growth, tumor weight, as well as the expression of AKK1, Notch3, GLS, MMP-2, MMP-9, and Ki-67 percentage." (PMID 38169546, 2024). "We hypothesize that in the double-mutant tumors deleted for LDHA and GLS, HFSCs failed to up-regulate alternative pathways to substitute for the loss of glutaminolysis and lactate utilization as compensatory mechanisms and, as a result, failed to fuel the TCA cycle leading to tumor growth." (PMID 39303037, 2024). "It is worth noting that although GLS inhibition significantly reduced PDAC cell proliferation in short term assays in vitro, there is no significant tumor growth delay in mouse models of PDAC." (PMID 33117704, 2020). "These tumor cells utilize glucose-derived glutamate to synthesize glutamine in a GLS-independent manner, and hence do not respond to glutaminase inhibition." (PMID 31652923, 2019). "When biological subtypes were considered, GLS and GLS2 proteins remained positively correlated, albeit weakly, in the high proliferation/luminal B tumours (p = 0.045), but not the low proliferation/luminal A tumours (p = 0.115)." (PMID 34439127, 2021). "GLS expression is increased post-castration in LNCaP and LAPC4 xenografts, and pharmacological inhibition of GLS1 reduces the tumor burden in PC3, but not LNCaP xenografts, highlighting the dependency on glutamine metabolism in AR-negative, hormone-insensitive prostate cancer." (PMID 35127483, 2021). "Furthermore, the single‐cell flux estimation analysis (scFEA) of glutamine metabolism revealed that glutamate‐to‐glutathione (Glu‐GSH) flux, downstream of GLS, rather than Glu‐to‐2‐oxoglutarate flux plays a key role in regulating the immune response of CRC cells in the tumor." (PMID 39482885, 2025).
infection (30 papers, 2009 to 2025). The state of being infected such as from the introduction of a foreign agent such as serum, vaccine, antigenic substance or organism. "GLS-1 or GFP were co-expressed with GLD-3L by co-infection with baculoviruses encoding the individual fusion proteins." (PMID 19461891, 2009). "Our data are consistent with a model whereby MNV uses the NS1/2 protein to upregulate GLS activity during infection of macrophages, which increases glutamine catabolism and promotes viral propagation." (PMID 38976719, 2024). "After normalization, we still observe increased GLS activity during infection with all NS1/2 mutant viruses." (PMID 38976719, 2024). "Our data are consistent with a model whereby MNV uses the NS1/2 protein to upregulate GLS activity during infection of macrophages, which increases glutamine catabolism." (PMID 38187600, 2023). "The transcription levels of GSL genes were much lower in immature fruits during the infection process compared to those in mature peach fruit, indicating the weak induction of GLS genes in more pathogen-resistant fruit tissues." (PMID 38140486, 2023). "Compared to the uninfected cells, a time dependent increase in glutaminase expression was observed during 8 h, 24 h, 48 h and 5 d of de novo infection of primary HMVEC-d cells by KSHV (lanes 1–6)." (PMID 25299066, 2014). "This is slightly less than the 1.75-fold increase in GLS activity observed during MNV infection." (PMID 38976719, 2024). "To determine whether caspase cleavage of NS1/2 mediated increased GLS activity, we measured GLS activity during infection with recombinant MNV mutants." (PMID 38976719, 2024). "This is slightly less than the 0.75-fold increase in GLS activity observed during MNV-1 infection." (PMID 38187600, 2023). "In addition, GLS mRNA and protein expression gradually increased early in Brucella infection (0-12 h), peaked at 12 h, and gradually decreased later in the infection (12-48 h)." (PMID 37325614, 2023). "In vitro and in vivo pharmacological inhibition of glutaminase (GLS), which catalyzes the first reaction in the primary pathway for the catabolism of glutamine, significantly increased the susceptibility to infection demonstrating the role of glutamine metabolism to L. donovani infection." (PMID 32214337, 2020). "In addition to altering cellular glucose metabolism, ADWT infection of human bronchial epithelial cells results in increased glutamine consumption and activity of glutaminase (GLS)." (PMID 31319842, 2019). "Protein lysates were obtained from cells on day 5 post‐infection, when cell numbers were still equivalent between FAHD1 KD cells and controls, and analysed for levels of FAHD1 and GLS." (PMID 35962472, 2022). "Next, we assessed the in vivo impact of a specific GLS inhibitor (BPTES, 12.5 mg/kg every two days) or providing glutamine supplementation at a daily dose of 500 mg/kg during the early steps of the infection." (PMID 32214337, 2020). "To study the exact metabolic pathways involved, we examined the temporal changes in the expression of glutamine metabolism-related enzymes, including glutaminase (GLS), GDH and CAD, in host cells during infection." (PMID 32085644, 2020). "Glutaminase (GLS) chemical inhibition was performed using BPTES and glutamine was administered throughout infection." (PMID 32214337, 2020). "To determine the impact of glutaminolysis impairment during L. donovani infection in vitro, we have pharmacologically inhibited GLS, using BPTES, 48 hours post-infection." (PMID 32214337, 2020). "Medium containing CB839, a non-competitive GLS inhibitor, was added after infection and infectious titers were measured after 8 hours by plaque assay." (PMID 38976719, 2024). "Here we found that the pan-GLS/GLS2 inhibitor SU1 was highly effective at blocking HCoV-229E replication, while the GLS-specific compound UP4 was relatively ineffective, consistent with our findings that infection of MRC5 cells predominantly upregulates the GLS2 isoform." (PMID 39662828, 2024).
infection (continued). "Medium containing CB839, a non-competitive GLS inhibitor, was thus added after infection and infectious titers measured after 8 hours by plaque assay." (PMID 38187600, 2023). "Among these genes, glutaminase 1 (GLS1) and glutamate dehydrogenase 1 (GLUD1) enzyme activity and protein expression were elevated, while glutamic oxaloacetic transaminase (GOT1 and GOT2), glutamate pyruvate transaminase 2 (GPT2), and glutamine synthase (GS) were unchanged during PoRVA infection." (PMID 38905309, 2024). "Host caspases cleave NS1/2 late during infection but glutaminolysis is upregulated to sustain genome replication early in infection, thus taken together these data suggest that the uncleaved precursor NS1/2 is the predominant form mediating the increase in GLS activity." (PMID 38976719, 2024).
neurological diseases (10 papers, 2013 to 2026). "Recent reports identified de novo gain-of-function GLS mutations in two patients with neurological disease." (PMID 41000630, 2025). "Aberrant GLS activity can disrupt glutamine/glutamate homeostasis in the brain and cause neurological disease." (PMID 41000630, 2025). "Recent studies have implicated GLS, RAI1, GIPC1, MED15, EP400, MEF2A, and CNKSR2 in neurological diseases, with GLS, GIPC1, MED15, RAI1, and MEF2A sharing the same repeat loci reported in this study." (PMID 38871700, 2024). "Glutaminase (GLS), a pivotal enzyme in the glutamate synthesis pathway, catalyzes the hydrolysis of glutamine to produce glutamate and involved in the pathogenesis of various neurological disorders." (PMID 39567494, 2024).
hematological malignancies (7 papers, 2016 to 2023). "The consequences of glutaminase inhibition have been studied in solid cancers with promising results, but for hematological malignancies, data are still limited." (PMID 37228498, 2023). "To probe for the functional role of Gln in AML, we utilized the novel selective nanomolar potency GLS inhibitor CB-839, which is currently undergoing clinical evaluation as both a single agent and in rational combinations in solid tumors and hematologic malignancies." (PMID 27806325, 2016). "As glutamine metabolism often depends on mitochondrial glutaminase (GLS) activity, GLS has become a target molecule for developing new potent inhibitors for GLS and, as recently reported, CB-839 chemical compound has entered clinical trials for advanced solid tumors and hematological malignancies." (PMID 31139559, 2019).
liver (4 papers, 2020 to 2024). "Further investigation identified the GSKα/β pathway as a central regulator of this adaptive glutamine metabolism that enables lung SCC tumors to escape the effects of mTOR inhibition by upregulating glutaminase expression." (PMID 32083006, 2020).
hematologic cancers (3 papers, 2018 to 2025). "They found that GLS was overexpressed in breast, esophagus, head-and-neck, and hematologic cancers and was associated with poor prognosis." (PMID 35087740, 2021).
neurodegenerative disease (3 papers, 2012 to 2020). A disorder of the central nervous system characterized by gradual and progressive loss of neural tissue and neurologic function. "In addition to STAT1 and type I IFNs, dysregulated glutaminase has also been indicated in a few animal models of neurodegenerative diseases." (PMID 22479354, 2012).
brain disorder (2 papers, 2017 to 2024). A disease affecting the brain or part of the brain. "Interestingly, glutaminase has been linked to brain diseases such as HIV-1 associated dementia, multiple sclerosis, amyotrophic lateral sclerosis, and Alzheimer’s disease, as well as schizophrenia." (PMID 28439409, 2017). "The exact mechanism of how glutaminase contributes to brain disorders remains unclear." (PMID 28439409, 2017).
head and neck tumor (2 papers, 2023 to 2025). "Additionally, the upregulation of Glutaminase (GLS) is closely related to the clinical and pathological features of head and neck tumors." (PMID 40018039, 2025).
benign tumors (1 paper, 2020). "The importance of GLS-1 was also reassured by evaluation of expression of GLS-1 in malignant PGL tissues compared to benign tumors." (PMID 32150977, 2020).
cardiovascular diseases (1 paper, 2025). "GLS1 (glutaminase 1), a rate‐limiting enzyme catalyzing the conversion of glutamine to glutamate, is disordered in various cardiovascular diseases." (PMID 40289670, 2025).
peripheral neuropathy (1 paper, 2025). A disorder affecting the peripheral nervous system. "Recent studies showed that compounds with dual glutaminase inhibition and Nrf2 activation activities effectively prevent diseases such as chemotherapy-induced peripheral neuropathy." (PMID 40830312, 2025).
GLS also shares sentences with these, for which no sentence is quoted: Ataxia (7 papers); colitis (5); esophageal squamous cell carcinoma (4); lymph node metastasis (4); pancreatic adenocarcinoma (4); Cerebral ischemia (3); head and neck cancer (3); intrahepatic cholangiocarcinoma (3); adenocarcinoma (2); Anxiety (2); bacterial diseases (2); HIV dementia (2); lung squamous cell cancer (2); metastatic tumor (2); non-alcoholic steatohepatitis (2); plasmacytoma (2); rheumatoid arthritis (2); spastic ataxia (2); uterine corpus endometrial carcinoma (2); acute liver failure (1); adrenal gland neoplasm (1); adrenocortical carcinoma (1); African trypanosomiasis (1); alcohol (1); anemia (1); apneic episodes (1); bipolar disorder (1); bone cancer (1); bone metastasis (1); breast adenocarcinoma (1).
A further 72 diseases each share a sentence with GLS in 1 paper.